CD40 (CD40 molecule)
Diseases named in the same sentence as CD40 in open-access papers (continued):
Sharing a sentence is not in itself a finding about the gene and the disease.
tumor (continued). "Here, we set out to test the association between polymorphisms in the CD40 gene and breast carcinogenesis and tumor pathology." (PMID 21912605, 2011). "At least one previous study reported that a CD40 positive tumour cell line resistant to Fas cytotoxicity was susceptible to TNFR or CD40-mediated death." (PMID 21103345, 2010). "A link between inflammation and malignancy is supported by our finding that C4BP is expressed strongly in the reactive stroma at tumour margins in association with CD40 expression on tumour cells." (PMID 17225862, 2007). "Seventy-eight percent of the tumours were CD40 positive, with a highly significant association with both lower stage and lower grade (P<0.001)." (PMID 12592374, 2003). "While CD40 agonists have historically been associated with considerable toxicity, the development of tumour-targeted immunomodulators such as bispecific antibodies may offer a more tolerable means of targeting CD40." (PMID 39548315, 2025). "Additionally, CD40-positive EVs were prominent, potentially linked to anti-tumor immune responses under IL-6 signaling." (PMID 40106404, 2025). "MIP2 and CD40 were also identified as pro-tumor factors associated with angiogenesis." (PMID 40658605, 2025). "Overall, we can conclude that while inducing anti-tumour-associated Cd40 and Cd80 and reducing pro-tumorigenic VISTA, SFV also upregulated PD-L1 which could interfere with the therapeutic effect." (PMID 40547518, 2025). "However, the addition of the anti-CD40 causes a reorganization of the myeloid compartment by increasing the number of mature DCs in the tumor and the levels of MHC-II molecules in other APCs, such as macrophages and microglia." (PMID 40578365, 2025). "Furthermore, the expression of CD40 in human ESCC has been linked to tumor progression and lymph node metastasis." (PMID 40034693, 2025). "In BPR20 tumors treated with ARG2i/COX2i/NOS2i, an increase in CD45+ immune cell infiltration into the tumor was observed, corresponding with increases in gene transcripts associated with immune cell-mediated tumor growth control and inflammation (e.g., Ccl21a, Fasl, Cd8b1, Cd40, Cd4, Cxcl11)." (PMID 38312842, 2024). "Moreover, using CD40- and FcγR-humanized C57BL/6J mice harbouring MB49 or UPPL1541 tumours, it was shown that the human anti-CD40 agonist antibody 2141-V11 caused reduced tumour size and that this effect was enhanced by cotreatment with IL-15 [37▪]." (PMID 38630912, 2024). "Furthermore, we also found that administering the Ab directly into the tumor site circumvents the toxicity associated with systemic administration of anti-CD40 Abs and directs their activity to the tumor microenvironment." (PMID 38883779, 2024). "Conversely, the co-activation of Dectin-1 and the TNF receptor superfamily member CD40 with agonists alters the phenotype of pro-tumoral Tumor-Associated Macrophages (TAMs) within the tumor microenvironment, enhancing anti-tumor immunity and impeding tumor progression." (PMID 39590166, 2024). "targeting of TAMs by CD40 agonists is associated with re-education of immunosuppressive TAMs into cytotoxic effectors, ultimately leading to immune surveillance and reduction of tumor growth." (PMID 37810971, 2023). "Indeed, mAbs that bind CD40 activate DC, myeloid cells, as well as B cells and increase their ability to process and present tumor-associated antigens (TAA) to local cytotoxic T lymphocytes." (PMID 37046842, 2023). "Earlier investigations demonstrate that CD40 stimulation, in addition to activating tumor-associated immunosuppressive macrophages and T cells and inhibiting tumor progression, also remodels the TME and heightens the tumor’s responsiveness to checkpoint blockade therapies in various types of cancer." (PMID 37799714, 2023). "Importantly, immunotherapy with anti-CD40 or anti-PD1 antibody achieved a markedly improved outcome in tumor-bearing mice with PPARδ deficiency in B cells or treated with PPARδ inhibitor." (PMID 37291146, 2023).
tumor (continued). "Moreover, OVs have been designed with additional transgenes encoding CD40 ligand (CD40L), increasing local CD40 activation within the tumor microenvironment." (PMID 35027068, 2022). "Of note, improved antigen presentation and increased frequency of tumor associated DCs with high expression of CD40, CD80, and CD86 co-stimulatory molecules have been described in response to olaparib, together with enhanced transition of CD8+ T cells to the tumor site." (PMID 36428727, 2022). "Intratumoral delivery of the cytokine interleukin-2, had little effect by itself but when combined with anti-CD40, caused local regression and, importantly regression of a distal untreated tumor, possibly due to the induction of inflammation within the tumor." (PMID 35431929, 2022). "In this respect, it is worth mentioning that preclinical studies have shown that the intratumoral and systemic application of anti-CD40 antibodies is therapeutically equally effective, but that local application in the tumor is associated with fewer side effects." (PMID 36361658, 2022). "However, CD40 agonist exhibited partial therapeutic benefit in cDC1-deficient hosts and resulted in priming of tumor-specific yet atypical CD8+ T cells with a regulatory phenotype and that failed to participate in tumor control." (PMID 35393950, 2022). "Thus, we believe that our results are applicable to the use of CD40 agonists in the treatment of patients with active and measurable disease as well as patients with undetectable disease but who are at high risk for tumor recurrence." (PMID 34101617, 2021). "The observed association between CD40 expression and the type-I anti-tumor T-cell response could partially result from CD40+CD8+ T cells in the TME, since CD40 activation is fundamental for their memory generation." (PMID 34758832, 2021). "A previous study has showed PNPT1 as a tumor‐associated antigen in CD‐40‐activated leukemic cells." (PMID 33037736, 2020). "Similarly, another study showed robust tumor regression associated with increased CD8+ T-cell infiltration when anti-CD40 was combined with dual ANG2 and VEGF blockade." (PMID 33217955, 2020). "Interestingly, higher proportions of tumor‐infiltrating CD40+ or CD86+ pDCs were linked to longer PFS, whereas higher proportions of tumor‐infiltrating CD80+ cDC2s or pDCs foresaw worse clinical outcome as it was linked with shorter PFS." (PMID 33282290, 2020). "Overall, the results of repeated studies consistently showed that one dose of radiotherapy in combination with the immunoadjuvant anti-CD40 can generate an effective abscopal effect, causing significant tumor growth inhibition or complete regression, in both the locally treated and untreated tumors." (PMID 32331490, 2020). "Reduction of several layers of suppression in young tumor-associated CD4+ T cells may help account for the improved tumor response seen in young mice to IL-2/CD40 treatment." (PMID 30560130, 2018). "Assessment of expression of genes encoding the TNF receptor superfamily members as well as the immunoglobulin receptor superfamily revealed upregulation of genes encoding CD28, ICOS, 4-1BB, GITR, OX40, CD27 and CD40 within the NDV-injected tumours, with ICOS being most prominent." (PMID 28194010, 2017). "Also, in the case of Burkitt lymphoma, CD40 activation caused tumor growth inhibition, increased activity of Fas, and enhanced apoptosis of tumor cells." (PMID 25117071, 2014). "In a mouse model of renal cancer, the efficacy of IL-2/anti-CD40 agonist antibody was associated with conversion of the immunosuppressive tumor milieu to an immunogenic milieu which was rich of inflammatory chemokines including CXCL-9, CXCL-10, CCL-5, and CCL-3." (PMID 22778760, 2012).
tumor (continued). "In conclusion, our data demonstrated that the HER2‐targeting CD40 BsAb could achieve localised activation of CD40 in tumours while simultaneously minimising the toxicity associated with systemic CD40 activation, thereby addressing the challenges encountered in current clinical practice." (PMID 40726342, 2025). "Furthermore, tumor nest expression of CD40 protein, another B cell marker, was shown to associate with worse OS in our cohort supporting the likelihood of these tumor-infiltrating B cells as being adverse in raising anti-tumor immunity in SCLC." (PMID 39231924, 2024). "Therefore, the mutation of the CD40 gene may affect the expression of CD40 and play an anti-tumor role." (PMID 37691121, 2023). "Second, off tumor activation of CD40 and 41BB may cause dose limiting systemic inflammation." (PMID 35198053, 2022). "Agonistic anti-CD40 monoclonal antibodies (mAbs) are in clinical development based on the notion of directly activating APCs to stimulate immune responses either against intrinsic antigens, e.g., tumor-associated antigens (TAAs), or as an adjuvant to protein or peptide vaccines." (PMID 35095862, 2021). "For example, the CD40 agonist antibody CP-870893 with tumor targeting function can activate M1 receptor (CD40) during cancer treatment, thereby causing macrophages to rapidly infiltrate tumors and promote tumor matrix depletion in the immunosuppressive tumor microenvironment." (PMID 34683963, 2021). "In addition, CD40 activates tumor-associated macrophages to the activated M1 phenotype." (PMID 33572196, 2021). "Thus, mCD40L expression in transduced tumour cells may induce apoptosis in CD40-expressing carcinomas, liberating tumour associated antigens for uptake by tumour-infiltrating dendritic cells." (PMID 31941968, 2020). "However, CD40 stimulation has also been implicated in promoting tumor growth and immune evasion." (PMID 27385210, 2016). "On one hand, up-regulated production of cytokines in response to CD40 activation can enhance the immunogenicity through augmented presentation of tumor-associated antigens by the tumors and increasing recruitment of immune cells into tumor sites, which was observed after CD40L stimulation." (PMID 25117071, 2014). "Further, the requirement of CD40 agonistic antibodies for FcR-mediated cellular cross-linking opens the possibility of generating bi-specific antibodies that on the one hand target a tumor associated antigen and on the other hand comprise an antiCD40 antibody fragment." (PMID 23840967, 2013). "Here, CD40 activation of autologous B-CLL tumor cells may upregulate tumor-associated antigens, such as survivin or RHAMM (receptor for hyaluronic acid-mediated motility) which may be expressed in vivo by B-CLL SP cells, resulting in their depletion following immunization." (PMID 19922650, 2009). "A phase I clinical trial also showed that CD40 activation enhanced anti-tumor immunity in patients with castration-resistant PCa, further validating A3C’s tumor-suppressive role and its potential as a target for CD40-related immunotherapy." (PMID 41514678, 2026). "Tumor-bearing mice were treated with anti-PD-1 or CD40 agonist antibodies and cell depletion or cytokine blocking antibodies to define mechanisms of action." (PMID 41676732, 2026). "Activation of the CD40 pathway in the tumor microenvironment was shown by increased infiltration of antigen-presenting, plasma and follicular helper T cells, dendritic cell maturation, interferon-γ signaling and circulating immune markers." (PMID 42067655, 2026). "Unexpectedly, both CD8+ T cells and NK cells, but not CD4+ T cells, were required for the efficacy of CD40 agonist, even though CD8+ T cells cannot directly recognize antigen presentation-deficient tumor cells." (PMID 41676732, 2026). "Instead, these lymphocytes control tumor growth via secretion of IFNγ, as depletion of IFNγ inhibited the therapeutic effect of CD40 agonist." (PMID 41676732, 2026).
tumor (continued). "Known to promote M2 to M1 polarization in monocytes and macrophage populations, reduced CD40 expression in pediatric immune cells results in reduced anti-tumor response." (PMID 39796780, 2025). "Activation of toll-like receptor, interferon, and CD40 signaling pathways promotes M1 macrophage differentiation, enhancing antigen presentation, directly phagocytosing tumor cells, and recruiting CD8+ T cells and NK cells." (PMID 40176817, 2025). "CD40 activates antigen-presenting cells (APCs) that can elicit an immune response to tumor antigens." (PMID 40430543, 2025). "Pioneering studies in pancreatic cancer patients revealed that anti-CD40 agonistic antibodies not only stimulate macrophage-mediated tumor cell engulfment but also enhance dendritic cell (DC) cross-presentation and T-cell priming." (PMID 40458409, 2025). "Recent studies exploring the combination of CSF-1R inhibitors with ICIs and CD40 agonists have shown promise in enhancing anti-tumor immunity." (PMID 40764998, 2025). "Beyond this, the axis markedly enhances B cell activation and plasma cell transition, augments tumor-specific antibody production, upregulates the costimulatory molecule CD40 to strengthen B cell–T cell crosstalk, and amplifies T cell activation and expansion." (PMID 41561762, 2025). "Activated tumor-specific CD8+ T cells are able to directly target CD40-expressing cancer cells within the tumor microenvironment, provided that these cells display tumor antigens." (PMID 40397730, 2025). "On the contrary, immature neutrophils (CD10- CD16-), PMN-MDSC, PD-L1+ M-MDSC, and PD-L1+ e-MDSC, pDC expressing ICOS-L, CD86, or CD40 as well as CD16- NK cell proportions with limited antitumoral potential dominated in tumor tissues." (PMID 41221283, 2025). "Critically, CD40 expression was one of the distinguishing markers of the B cells infiltrating the tumour microenvironment, and the cell communication analysis highlighted the CD40LG (INS+ FOSlow, INS+) − CD40 (B cell) interaction." (PMID 40438247, 2025). "Bispecific antibodies that target tumor antigens, fibroblast activation protein on stromal cells, or other receptors such as 4–1BB can also cross-link CD40 agonists, promoting antitumor immunity in the tumor microenvironment." (PMID 41182434, 2025). "Here, we show that targeting CD40 with a local injection of an agonistic antibody is safe and enhances the anti-tumor effect of the Delta-24-RGD in DMG orthotopic mouse models." (PMID 40578365, 2025). "Selective depletion of Ly6G+ cells unexpectedly compromised agonistic CD40 antibody efficacy, accelerating tumor growth and reducing survival in PDAC-bearing mice." (PMID 40060615, 2025). "Compared to the control group, the cell number of the CD40+ DCs (CD45+CD3e−MHCII+CD40+CD11c+) in the tumor draining lymph nodes was significantly reduced in all treatment groups except α-PD-1 + α-CTLA-4 group." (PMID 39871312, 2025). "Among the 48 primary tumor samples, ASNS, CD40, CHD7, and ITPKB mutations were exclusively identified (n = 1 each; p = 0.0147) and were absent in the 67 metastatic samples." (PMID 40361470, 2025). "Agonistic CD40 monoclonal antibodies have been used to stimulate antigen-presenting cells (APCs) and encourage anti-tumor T cell replications." (PMID 41155910, 2025). "Successful adoptive T cell therapy relies on the presence of cDC1s within the tumor to provide T cell homing chemokines and support adoptively transferred T cell expansion via CD40- and CD70-dependent mechanisms." (PMID 41430039, 2025). "Recent studies have shown that prophylactic immunization of tumor-bearing mice with tumor antigen-pulsed CD40-activated B cells can induce protective antitumor immunity against B16, leading to reduced growth of F10 melanoma and E.G7 lymphoma." (PMID 41285707, 2025). "FGL2, primarily produced by tumor-infiltrating macrophages/monocytes and DCs, downregulates CD40 and CD86 on CD11+ DCs through FcγRIIB/III-mediated signaling." (PMID 41470247, 2025).
tumor (continued). "In our bulk analysis, high CD4/CD8 expression was observed in 52% of tumors with high CD40 expression, suggesting that CD40 was expressed not only in T cells but also in tumor cells within the tumor microenvironment." (PMID 41182434, 2025). "This CD40LG-CD40 interaction directly inhibits the proliferation of CD40-expressing neoplastic cells and simultaneously activates immune-mediated tumor suppression through indirect mechanisms." (PMID 40469184, 2025). "This was attributed to the immunostimulatory effects of the Christensenellaceae species, which facilitated the migration of mregDC (PD-L1+CD40+ DCs) to the tumor-draining lymph nodes to prime anti-tumor CD8+ T-cell responses." (PMID 41375050, 2025). "Recent studies investigating the combination of CD40 agonists with gemcitabine and nab-paclitaxel in PDAC have shown that tumor extrinsic immune signatures associate with improved outcomes, consistent with the potential benefit of CD40 agonism." (PMID 41061701, 2025). "These exosomes inherit the antigen-presenting abilities of their parent cells and can be enriched with tumor-associated antigens (TAAs), MHC molecules, and co-stimulatory signals such as CD40, CD80, and CD86." (PMID 40754671, 2025). "Anti-CD40 antibodies have shown significant anti-tumor activity as single agents in several preclinical models including PDAC and breast cancer 206-208." (PMID 40083710, 2025). "When administered alongside tumor antigens or checkpoint blockade therapies, CD40 agonists have demonstrated synergistic antitumor effects in preclinical models and early clinical trials." (PMID 40667699, 2025). "Among these genes, CD40 is an important immunomodulatory molecule, which promotes anti-tumor immune responses by regulating the function of immune cells." (PMID 41417784, 2025). "Preclinical studies have shown that the agonistic anti-CD40 antibody CP-870,893 reprograms TAMs into M1-like effector cells with enhanced antigen-presenting capacity, thereby restoring tumor immune surveillance and promoting tumor regression in murine models." (PMID 40563367, 2025). "Activation of CD40 through agonistic antibodies initiates a cascade of immunological events critical for effective anti-tumor immunity." (PMID 40585246, 2025). "The following three CD40 agonist antibodies each act to modulate the TME to improve anti-tumor immunity, despite differences in their designs and effects." (PMID 40872551, 2025). "Apparently, the senescent-like state induced by RMC-7977 and palbociclib facilitates CD4 T cell–mediated surveillance of residual tumor cells upon the addition of the CD40 agonist." (PMID 40299790, 2025). "The CSFR1 inhibitor PLX3397 avoids the presence of cytokines and chemokines at the tumor site in Delta-24-RGD+anti-CD40-treated mice." (PMID 40578365, 2025). "Therapeutic activation of neutrophils by TNF-α, CD40 agonist, and tumor-binding antibody contributes to massive ROS production and tumor eradication independently of T cells." (PMID 40050933, 2025). "The data demonstrate an increased survival rate and duration in the case of tumor-bearing mice treated with free anti-CD40 inhalation compared to the placebo group." (PMID 40278452, 2025). "This study utilizes a drug delivery system and a fiducial marker, the LIFE biomaterial, to provide sustained local delivery of a monoclonal antibody (anti-CD40) directly at the tumor site throughout the treatment period." (PMID 41155910, 2025). "In line with in vitro findings, tumor-infiltrating cDC1s exhibited elevated expression levels of CD40, CD80, and CD86 following DS treatment." (PMID 40625660, 2025). "Anti-CD40 antibodies exert tumor-suppressive effects by engaging tumor-infiltrating macrophages and increasing levels of CCL2 and IFNγ, thereby enhancing tumor cell elimination." (PMID 40343509, 2025).